IHH (Indian hedgehog signaling molecule)
Diseases named in the same sentence as IHH in open-access papers (continued):
Sharing a sentence is not in itself a finding about the gene and the disease.
cancer (22 papers, 2010 to 2025). A tumor composed of atypical neoplastic, often pleomorphic cells that invade other tissues. "By focusing in on the associated genes we are also able to pinpoint the location of potential regulatory elements such as the promoter proximal, intronic and distal elements associated in cancer cells with the IHH locus (top)." (PMID 28859074, 2017). "In addition, we also detected multiple PUD risk, cancer-related genes (for example, IHH, GNAS, NHEJ1, JUP and MECOM), which provided potential targets contributing to the different outcomes of PUD or GC." (PMID 38036781, 2023). "Thus, abnormal expression of two trigger molecules IGF/IHH may be one of the causes of cancer development and of maintenance of the cancer properties of TISCs." (PMID 28031533, 2017). "To clarify this, we used GDC-0449 (Vismodegib), a selective IHH signaling inhibitor and pharmaceutical drug for a variety of cancers, to inhibit the IHH pathway." (PMID 38409269, 2024). "The lower expression of IHH, BOC, RAB23, miR-195-5p, and miR-6738-3p was significantly associated with more advanced cancer stage." (PMID 33811245, 2021). "In epithelial-origin cancers, EBV infection has been strongly associated with the gain of CpG methylation, and methylation of tumor suppressor genes such as p14, p16, IHH, TRADB, PTEN or SSTR1 is likely the key mechanism of oncogenesis." (PMID 32841292, 2020). "IHH is expressed in the adult colon and prostate and restrains the growth of colon and prostate cancers." (PMID 32108165, 2020). "As most of the cell lines were generated from patients with late stage or metastatic adenocarcinomas, the dearth of cancer lines with upregulated IHH mRNA corroborates the in situ results of IHH mRNA in more indolent lepidic histologies." (PMID 32108165, 2020). "We have shown both in the mouse model and in human specimens that IHH is highly expressed in the metastatic cancer cells." (PMID 30373214, 2018). "We further explored this by examining PGR mRNA levels in these cancers and found that loss of PGR and IHH expression were correlated." (PMID 23785665, 2013). "These drugs, such as Cyclopamine, Vismodegib etc. are only effective when a cancer cell with excessive Hedgehog pathway activation, is encountering over-expressed hedgehog ligands (SHH, IHH or DHH) or has mutated PTCH1 or SMO in membrane." (PMID 23935937, 2013). "In bone metastatic breast cancer, RUNX2 promotes cancer cell survival and growth by activating expression of IHH and interacts with the TGFβ/BMP signal transduction pathway to parathyroid hormone-related protein (PTHrP)." (PMID 20465837, 2010). "Notably, introducing an IHH antagonist as a cancer therapeutic drug in a clinical trial significantly reduced the proliferation and differentiation of Gli1+ CPs, thereby harming bone growth." (PMID 38409269, 2024). "Abnormal activation of the IHH-dependent signaling pathway due to increased expression of IGF leads to development defects and transformation of stem cells in TISCs, resulting in cancer development." (PMID 28031533, 2017). "Furthermore, we also observed that genes in the pathway “Proteoglycans in cancer” (KEGG), namely RPS6 and IHH, were significantly over-represented." (PMID 40232348, 2025). "However, they occurred independently of tissue invasion (perineural, lymphovascular, fat, bone, muscle, and mucous acini) and proteins related to the HH pathway (SHH, IHH, SMO, and GLI‐1), which contributed to the morphogenesis of this rare cancer." (PMID 40930949, 2025). "Although the molecular mechanism underlying Hh signaling activation in the metastatic niche is currently not well characterized, our data suggest that elevated IHH expression in the metastatic cancer cells may be responsible." (PMID 30373214, 2018). "Specifically IHH was distinctly down-regulated in most high grade cancers regardless of histotype." (PMID 23785665, 2013).
skeletal dysplasia (3 papers, 2016 to 2025). Any Mendelian diseases that affects growth and development of the skeleton. "The DNA sequence analysis [Invitae Skeletal Dysplasia Panel] identified variants in TBX6 and IHH, which probably correlate with our patient's distinct phenotypes." (PMID 35846898, 2022).
IHH also shares sentences with these, for which no sentence is quoted: holoprosencephaly (2 papers); infection (2); lung adenocarcinoma (2); adenocarcinoma (1); chondrodysplasia (1); chondroma (1); chronic myelogenous leukemia (1); cleidocranial dysplasia (1); colonic adenomas (1); congenital cataracts (1); Constipation (1); Ductal Carcinoma (1); dwarfism (1); endocrine disorders (1); epidermoid carcinoma (1); familial hypercholesterolemia (1); glioma (1); invasive breast carcinoma (1); laurin-Sandrow syndrome (1); liver cancer (1); lymphoma (1); mastitis (1); medulloblastoma (1); multiple synostoses syndrome 2 (1); Obesity (1); osteosclerosis (1); polydactyly (1); Polysyndactyly (1); salivary gland tumors (1); small intestinal adenomas (1).
A further 1 disease shares a sentence with IHH in 1 paper.